HOTAIR (HOX transcript antisense RNA)
Diseases named in the same sentence as HOTAIR in open-access papers (continued):
Sharing a sentence is not in itself a finding about the gene and the disease.
cancer (continued). "Therefore, HOTAIR expression level is a potential biomarker for diagnostic and therapeutic purposes in several cancers." (PMID 25859406, 2015). "Based on this rationale, we hypothesized that one of the mechanisms by which HPV16 E7 mediates its causal effect of activation of cancer-related pathway genes in CaCx pathogenesis, is through interplay with lncRNA HOTAIR." (PMID 26152361, 2015). "All of these indicated an important role of HOTAIR genetic variants in cancer susceptibility." (PMID 26384301, 2015). "It is unclear, however, whether HOTAIR is associated with an aberrant DNA methylation profile in cancer and whether this robust DNA-based imprint mediates resistance to specific drugs." (PMID 26497652, 2015). "For example, aberrant expression of lncRNA HOTAIR was associated with various cancers such as breast, hepatocellular, gastric, colorectal, and pancreatic, and its expression was associated with survival and prognosis of cancer patients." (PMID 25925763, 2015). "In addtion, HOTAIR has been strongly associated with the invasion and metastasis of cancer cells." (PMID 25792974, 2015). "HOTAIR is one of the most well studied examples of lncRNA implicated in cancer." (PMID 25954300, 2015). "Many lncRNAs such as HOTAIR, which has been implicated in several cancers, such as lung cancer, gastric cancer, esophageal squamous cell carcinoma, colorectal cancers, have already shown their potential as novel independent biomarkers for early diagnosis and prognosis prediction in cancer." (PMID 25435812, 2014). "In summary, up-regulation of HOTAIR is associated with adverse survival in many types of cancer, and HOTAIR may serve as an effective prognostic biomarker for diagnosis of cancer." (PMID 25303230, 2014). "Dysregulation of HOTAIR in various cancers is associated with metastasis and tumor progression." (PMID 25334066, 2014). "In summary, the high level of HOTAIR is intimately associated with an adverse OS in numerous cancers, suggesting that HOTAIR may act as a potential biomarker for the development of malignancies." (PMID 25303230, 2014). "Although HOTAIR and its association in cancer metastasis and prognosis of diverse cancers have been suggested in several studies 14–22, its functions in SCLC remain unclear." (PMID 24591352, 2014). "In these cancers, HOTAIR was also shown to be associated with metastasis and/or poor prognosis." (PMID 24130837, 2013). "HOTAIR (HOX transcript antisense intergenic RNA) has been implicated in several cancers; however, its role in non-small cell lung cancer (NSCLC) is unknown." (PMID 24103700, 2013). "Conversely, loss of HOTAIR expression reduced cancer invasiveness suggesting that lncRNAs, particularly HOTAIR, might significantly alter the epigenome of cancer cells." (PMID 21874119, 2011). "TUG1, NEAT1,HOTAIR, and CCAT1are examples of lncRNAs that might potentially cause cancer." (PMID 39512820, 2024). "Additionally, the assessment of HOTAIR expression in tumor samples could help in better recognition of the role of these polymorphisms in cancer progression, which ought to be investigated further." (PMID 38587571, 2024). "However, they revealed that HOTAIR is suspected to be a cancer-causing oncogene." (PMID 37776415, 2023). "Many studies reported that HOTAIR polymorphisms could affect cancer biology." (PMID 36924407, 2023). "For example, the expression of lncRNA HOTAIR is significantly associated with poor prognosis in lung, colon and primary breast cancers, which implies that it may be used as biomarkers for cancer diagnosis and prognosis, as well as potential treatment targets for various cancer types." (PMID 37614816, 2023). "Therefore, significant up-regulationof HOTAIR obtained from BC tumour samples comparedto BC cell lines, in this study, may explain the molecularmechanism causing poor prognosis of this cancer." (PMID 31721532, 2020).
cancer (continued). "Nonetheless, the role of HOTAIR in the regulation of vasculogenic mimicry, a novel cancer hallmark which involves the formation of patterned three-dimensional (3D) channel-like networks by tumor cells, is unknown in human cancers." (PMID 32466537, 2020). "However, the role of HOTAIR in vasculogenic mimicry and the underlying mechanisms are unknown in human cancers." (PMID 32466537, 2020). "These deficiencies may fail to correctly reveal how HOTAIR polymorphisms affect the risk of cancer." (PMID 29463216, 2018). "Therefore, we speculated polymorphisms in HOTAIR may also be related to cancer risk by modifying the secondary structure of HOTAIR then indirectly involved the relevant signaling pathways." (PMID 29463216, 2018). "Together, these results provide a roadmap for future mechanistic studies of structure-function relationships in HOTAIR and its contribution to gene regulation in cancer." (PMID 42239237, 2026). "Along with dysregulated expression of its target transcripts in human cancers, HOTAIR was as well repeatedly reported to be overexpressed highlighting a role for this lncRNA in carcinogenesis or related cancer-associated events." (PMID 41535654, 2026). "For example, HOTAIR is overexpressed in several cancers, recruiting Polycomb Repressive Complex 2 (PRC2) and other epigenetic regulators to suppress tumor suppressor genes, thereby facilitating proliferation and invasion." (PMID 40621472, 2025). "This discovery deepens our understanding of HOTAIR's molecular mechanisms across various cancer types and provides a new direction for future studies into HOTAIR's function in other tumor types." (PMID 40235720, 2025). "Through a series of experiments, we confirmed the direct interaction between HOTAIR and miR‐375, demonstrating that HOTAIR enhances immune evasion by modulating PD‐L1 expression, thus increasing cancer cell resistance to T cell‐mediated immune attacks." (PMID 40235720, 2025). "For example, lncRNA HOTAIR binds to the Notch1 receptor and inhibits its signal transduction, thereby promoting malignancy in various cancers." (PMID 40621472, 2025). "HOTAIR has gained a lot of attention, because of its role in the development and progression of different types of cancers." (PMID 39285617, 2025). "HOTAIR employs several mechanisms to upregulate PD-L1 expression and promote immune evasion in cancer." (PMID 41221298, 2025). "It is even more interesting to establish if, once nuclear, YBX1 in turn promotes HOTAIR induction, imposing additional advantage to invasive cancer cells." (PMID 40855961, 2025). "The upregulation of lncRNA with oncogenic potential such as HOTAIR, MALAT1, PCAT1, H19 have been reported in various cancer types and have been associated with various processes contributing to cancer development." (PMID 39912983, 2025). "HOTAIR expression correlates with tumor grade and prognosis in various cancers and modulates oncogenic pathways, including those governing migration and metastasis." (PMID 41256331, 2025). "This FOXC2-mediated regulation of HOTAIR promotes chromatin remodeling, enhancing cancer cell invasiveness." (PMID 40781106, 2025). "In cancer, ASOs against HOTAIR have shown the ability to modulate the TME, thereby inhibiting tumor growth." (PMID 41361062, 2025). "HOTAIR and EZH2 have been implicated in significant pro-tumorigenic roles across various cancer types, and their expression is closely associated with sensitivity to platinum-based chemotherapy." (PMID 41353219, 2025). "HOTAIR regulates the proliferation, colony formation, migration and self-renewal capacity of cancer stem-like cells." (PMID 40868070, 2025). "Several studies have shown that HOTAIR reprograms chromatin to promote cancer metastasis and transcriptional silencing of metastasis suppressor genes." (PMID 40868070, 2025).
cancer (continued). "For example, the administration of curcumin also exerts an antitumor effect in several types of cancer by inhibiting the expression of HOTAIR, an important oncogenic lncRNA." (PMID 40282449, 2025). "Until now, HOTAIR activity has been found to facilitate the metastatic potential of cancer cells, by regulating the expression of VEGF, MMP‐9, and vimentin." (PMID 39285617, 2025). "Specifically, we observed that HOTAIR overexpression led to an increase in cell viability, a result that is consistent with findings reported in various cancer models." (PMID 40072116, 2025). "Dysregulated HOTAIR expression has been shown to play a role in tumor initiation, growth, angiogenesis, cancer progression, recurrence, drug resistance, and poor prognosis in most solid cancers." (PMID 40686703, 2025). "Recent studies conducted in a plethora of cancers showed the success of CRISPR-Cas9 technology to effectively knock out the expression of HOTAIR, NEAT1, XIST, TUG1, and UCA1 and to effectively upregulate the expression of MEG3." (PMID 40282449, 2025). "This discovery positions HOTAIR as a significant therapeutic target for cancer treatment by inhibiting abnormal metabolism." (PMID 40072116, 2025). "HOTAIR functions as an antioxidant regulator lncRNA and prevents the cancer cell from exceeding the ROS level that would trigger apoptosis." (PMID 40563255, 2025). "After confirmation that HOTAIR participates in the regulation of aberrant metabolism, it opens an opportunity window as a therapeutic target for the treatment of cancer." (PMID 40072116, 2025). "HOTAIR is observed to be upregulated in different cancers and is demonstrated to be negatively involved in regulating metastasis-suppressing genes which induces tumor malignancy." (PMID 39912983, 2025). "A recent study reported that soy derived isoflavones are potent modulators of multiple signaling pathways, including HOTAIR, in cancer prevention and treatment." (PMID 40686703, 2025). "For example, HOTAIR was found to be highly expressed in breast cancer tissues and showed a significant increase in cancer cell lines under hypoxic conditions." (PMID 40277941, 2025). "Homeobox (HOX) Transcript Antisense Intergenic RNA (HOTAIR) (chromosome 12q13.13) is highly expressed in cancer tissues and plays a role in tumor progression, invasion, and metastasis." (PMID 40231344, 2025). "In cancer, HOTAIR contributes to aberrant transcription, chronic inflammation, and treatment resistance via NF-κB–dependent pathways." (PMID 41567340, 2025). "These lncRNAs, which include MALAT1, H19, HOTAIR and others, have been found to be important contributors to the development and spread of cancer." (PMID 39912983, 2025). "The study found significantly higher levels of HOTAIR in EC tissues compared to adjacent normal tissues, with high HOTAIR expression correlating with poorer survival rates and advanced cancer characteristics." (PMID 38981872, 2024). "We found that HOTAIR genes are highly expressed in a total of seventeen cancers and lowly expressed in one cancer by TIMER database." (PMID 38696320, 2024). "HOTAIR has been found to be upregulated in various types of human cancers and is involved in tumour progression and metastasis." (PMID 38506091, 2024). "Conversely, measures directed at repression of HOTAIR expression and activity are related to attenuation of tumorigenesis and cancer progression." (PMID 38366205, 2024). "For example, lncRNAs like MALAT1 and HOTAIR have been found to interact with mitochondrial components and copper transporters, thereby modulating the sensitivity of cancer cells to cuproptosis." (PMID 39325172, 2024). "ANRIL, another lncRNA with disrupted expression in various cancers, mirrors HOTAIR’s impact on TNBC’s angiogenesis." (PMID 39286016, 2024). "Like other lncRNAs, HOTAIR recruits chromatin-modifying proteins and influences the epigenome of cancer." (PMID 38434620, 2024).
cancer (continued). "Consistent with the results of our study, HOTAIR was highly expressed in cancer tissues and positively correlated with cancer proliferation and migration in multiple tumor cohorts." (PMID 38696320, 2024). "In conclusion, our pan-cancer analysis offers a comprehensive overview of the oncogenic roles played by HOTAIR across various human cancers." (PMID 38696320, 2024). "In this manuscript, we describe different mechanisms of antitumor drug resistance in which HOTAIR is involved and suggest its potential as a therapeutic predictive biomarker for the management of cancer patients." (PMID 38887279, 2024). "In summary, it was demonstrated that HOTAIR plays a pivotal role in dictating radioresistance and cancer progression in CRC and silencing HOTAIR promoted radiosensitivity in vitro and in vivo." (PMID 39055884, 2024). "Another widely-cited study showed that enforced HOTAIR gene expression in epithelial cancer cells induces chromatin reprogramming and an increased metastatic state, while inhibition of HOTAIR inhibits cancer invasiveness." (PMID 39484215, 2024). "Accumulating evidence suggests that HOTAIR is closely related to the proliferation and metastasis of human cancers." (PMID 38696320, 2024). "HOTAIR is a lncRNA that plays a role as an oncogenic molecule in different cancer cells, such as breast, gastric, colorectal, and cervical cancer cells." (PMID 39725668, 2024). "We conducted a comparative analysis to assess HOTAIR expression in pan-cancer by comparing it between tumor and normal samples by the Gent2 database." (PMID 38696320, 2024). "LncRNA HOTAIR (HOX Transcript Antisense RNA) has a role in regulating different biological processes in cancers." (PMID 38777995, 2024). "FSCN1 (rs852479, rs1640233) and HOTAIR (rs920778) were genotyped using TaqMan real-time PCR assay in 200 BC patients and 200 cancer-free controls, all representing Egyptian women." (PMID 38587571, 2024). "HOTAIR levels are aberrantly high in various prevalent human cancers, and a wealth of evidence implicates it in drug resistance, metastasis, and the initiation of cancer." (PMID 38329598, 2024). "HOTAIR is a widely studied lncRNA due to its pivotal role in many types of malignant tumors, including BC, where HOTAIR is highly expressed." (PMID 39148900, 2024). "HOTAIR lncRNA’s dysfunction promotes cancer cells’ proliferation, invasion, survival, metastasis, and drug resistance." (PMID 38157198, 2024). "HOTAIR, a long non-coding RNA encoded by the HOXC locus, serves as an oncogenic gene and has diverse roles in different malignant tumors." (PMID 38600608, 2024). "Sample differences lead to differences in the results of different databases, but as long as there are enough samples, the cancer-promoting role of HOTAIR is still plausible." (PMID 38696320, 2024). "We comprehensively investigated the effect of HOTAIR expression on tumor prognosis across human malignancies by analyzing multiple cancer-related databases like The Cancer Genome Atlas (TCGA) and Tumor Immune Estimation Resource (TIMER)." (PMID 38696320, 2024). "More recently, circulating HOTAIR can be considered a non-invasive biomarker due to its ability to predict the pathological features of cancer patients." (PMID 38887279, 2024). "Despite these limitations, our study provides valuable insights into investigating the function of HOTAIR in cancers and identifies potential targets and prognostic markers for CRC treatment." (PMID 38696320, 2024). "Among them, HOTAIR plays a critical role in both the initiation and progression of different types of human cancers, as well as in the modulation of resistance mechanisms, facilitated also by its functional interactions with different miRNAs." (PMID 38887279, 2024). "Our study characterizes HOTAIR expression patterns across different cancer types and highlights its potential value as a predictive biomarker while shedding light on further exploration into its prognostic and therapeutic potential." (PMID 38696320, 2024).
cancer (continued). "Some lncRNAs such as MALAT1 and HOTAIR increase the efficiency of metastatic cancer cells to develop in distal sites." (PMID 39725668, 2024). "HOTAIR acts as a molecular scaffold that recruits PRC2 and LSD1/CoREST/REST complexes directly into the promoter regions of multiple cancer-associated genes." (PMID 38339237, 2024). "We conducted a prognosis analysis using data obtained from PrognoScan and GEPIA to examine the relationship between HOTAIR expression levels and overall survival (OS) across various cancer types." (PMID 38696320, 2024). "Although the positive regulation of the Wnt/β-catenin and PI3K/AKT signaling pathways by HOTAIR has been well-documented in various types of cancer, the mechanisms interconnecting these pathways remain largely unexplored." (PMID 39273054, 2024). "Through genetic alteration analysis of HOTAIR, we observed that HOTAIR produced significant alterations in a variety of cancers." (PMID 38696320, 2024). "Both the expression of genes and the invasiveness of cancer are controlled by HOTAIR, which is dependent on PRC2-mediated histone methylation." (PMID 39512820, 2024). "In HNSCC, the expression of HOTAIR contributes to increased cancer cell invasion by repressing E-cadherin transcription and inducing EMT." (PMID 38600608, 2024). "In cancer tissue, HOTAIR acts as a molecular decoy for microRNAs (miRNAs) and RNA-binding proteins (RBPs) and directly regulated the target mRNA." (PMID 36980864, 2023). "High levels of HOTAIR expression were found to be correlated with both metastasis and poor survival rate, linking this lncRNA with cancer invasiveness and patient prognosis." (PMID 37384249, 2023). "This allows for the downstream effects of HOTAIR on gene regulation, chromatin remodeling, and cancer progression." (PMID 36997931, 2023). "To determine the relationship between the HOTAIR expression level and OS in patients with gastrointestinal system cancer, we classified studies according to the cancer type and analyzed the HR and 95% CI by using the fixed-effects model." (PMID 36924407, 2023). "Accumulating evidence suggests that HOTAIR can serve as a biomarker for cancer diagnosis and prognosis." (PMID 37526759, 2023). "Aberrant HOTAIR expression promotes metastasis, drug resistance, and tumor recurrence in patients with various cancers." (PMID 36997931, 2023). "Researchers mainly focus on the deregulation of HOTAIR in many forms of cancer due to its remarkable effect on epigenetic regulation at the genome-wide level." (PMID 36980864, 2023). "These facts suggest that HOTAIR is an excellent therapeutic target for broad-spectrum cancer treatment." (PMID 36924407, 2023). "It suggested that the possible mechanism by which HOTAIR promotes cancer growth is the regulation of LPR5 expression." (PMID 36816362, 2023). "This review also highlights the involvement of HOTAIR in drug resistance, which is a significant obstacle in cancer treatment." (PMID 36997931, 2023). "Although these studies revealed some aspects of HOTAIR function in cancer, the effect of HOTAIR on oxaliplatin resistance of GC remains poorly understood." (PMID 37621132, 2023). "A compelling interplay between HOTAIR and miR-130a has been observed in certain cancer types, including gallbladder cancer, where it promotes tumor invasion and metastasis." (PMID 38114755, 2023). "In this review, we describe the regulatory mechanisms that govern HOTAIR expression during cancer development and explore how HOTAIR drives BC development, metastasis, and drug resistance." (PMID 36997931, 2023). "In vitro experiments suggested that HOTAIR influences cell proliferation and regulates apoptosis, which are required for cancer growth." (PMID 38813489, 2023). "The increased expression level of HOTAIR is reported in many different types of cancer tissue samples with higher levels in the metastatic stage." (PMID 36980864, 2023).